MYCN (MYCN proto-oncogene, bHLH transcription factor)
Diseases named in the same sentence as MYCN in open-access papers (continued):
Sharing a sentence is not in itself a finding about the gene and the disease.
tumor (continued). "A recent study also reported a decrease in plasma MYCN copy number one week after surgery in five patients with MNA, proportional to the extent of tumour resection." (PMID 31088252, 2019). "In the clinically validated MYCN-amplified sample that went undetected by VCF2CNA, a follow-up review revealed that tumor heterogeneity and sampling bias most likely contributed to the discrepancy." (PMID 31316100, 2019). "The repression of ELOVL2 by the MYCN and PRC1 complex indicates PRC1 complex inhibition as a potential novel strategy to activate ELOVL2 tumor suppressive functions." (PMID 31856871, 2019). "In a follow-up study, it was demonstrated that MYCN repressed the expression of CCL2, thereby preventing homing of NKT cells to the tumor site in both mouse models and human patients." (PMID 31620124, 2019). "As predicted from this screen, treating MYCN amplified tumor in mouse models with topotecan resulted in TIS, a favorable SASP, and complete or partial tumor remission; however, its effects on immune cell recruitment was not analyzed." (PMID 29868482, 2018). "In summary, administration of MYCMI-6 to MYCN-dependent tumor-bearing mice resulted in the reduction of MYCN:MAX interaction, tumor cell proliferation and MVD and in induction of apoptosis in the tumor tissue without causing severe side effects." (PMID 29968736, 2018). "MYCN was found to be overexpressed in NSCLC, which was positively related to a more invasive tumor phenotype and poorer outcome." (PMID 29321960, 2018). "Contrasting our case, an inverse correlation of catecholamine levels and amplification of the MYCN protooncogene has been described, showing that MYCN-positive tumors have rather low urinary VMA and HVA despite a comparably larger tumor volume." (PMID 28818093, 2017). "Among the 10 amplification-based oncogenes, we identified that six genes (MDM2, MYC, MYCL, MYCN, NKX2-1, and SKP2) were amplified and overexpressed in ≥10 tumor samples." (PMID 28377632, 2017). "We assessed MYCN and ALK copy numbers from archived single tumor biopsies from the 10-patient pilot cohort in this study as the control measure for copy number detection using the paired plasma samples." (PMID 29156716, 2017). "Only a small number of tumor cells are required, compared with primary tumor biopsies, and FISH is more sensitive, counting the MYCN copy number in each single cell." (PMID 28367105, 2017). "Copy numbers assessed using cfDNA indicated a gain for MYCN in 2 patients (1 and 4) and for ALK in 3 patients (5, 7 and 8), whereas corresponding tumor gDNA revealed normal diploid status." (PMID 29156716, 2017). "There were apparent differences in age, sex, body weight, Kaup index, MYCN, VMA, HVA, NSE and tumor size (largest tumor dimension) between the groups." (PMID 28288594, 2017). "The only MYCN amplification was found in a case with a 9q deletion encompassing the PTCH1 locus, which strongly suggests this tumor belongs to the SHH subgroup." (PMID 26857864, 2016). "In our nf1a-/-;nf1b+/+;MYCN; EGFP fish, isotretinoin alone leads to reduced tumor growth, with essentially stable tumor size over 7 days of treatment at the highest dosages." (PMID 27130733, 2016). "In this study we explore the significance of MYCN, HMGA2, CDKN2A and DICER1 in NSCLC tumours by gene expression analysis." (PMID 26858029, 2016). "When focusing on the tumours with seemingly co-regulated HMGA2 and MYCN expression, we found a significantly better outcome when both genes were downregulated compared to the remainders." (PMID 26858029, 2016). "They show significant differences to immature NT (NB/GNBN) concerning age at diagnosis, stage, localization, tumor volume, mIBG-uptake, catecholamine metabolite excretion, NSE, and status of molecular markers (MYCN and 1p)." (PMID 27465021, 2016).
tumor (continued). "Gene expression of MYCN, HMGA2, CDKN2A and DICER1 were investigated with RT-qPCR in surgically resected NSCLC tumour tissue from 175 patients." (PMID 26858029, 2016). "Extra-chromosomal MYCN amplicons have been shown to be subjected to micronucleus-mediated oncogene elimination during TIS and in spontaneously occurring senescent tumor cells in NB." (PMID 26657295, 2016). "However, no driving oncogene such as MYCN has been linked to tumor formation in these mice." (PMID 27769070, 2016). "Overall this study suggests a regulatory circuit in which MYCN by elevating TFAP4 expression, cooperates with it to control a specific set of genes involved in tumor progression." (PMID 27448979, 2016). "A study showed combined treatment of crizotinib and an mTOR inhibitor led to reduced tumor growth and prolonged survival in ALK F1174L/MYCN-positive models compared to single agent treatment." (PMID 26786851, 2016). "In tumours with apparent co-regulation of expression of HMGA2 and MYCN, there was a significantly better outcome when both genes were downregulated compared to the alternatives (log rank test, p = 0.040)." (PMID 26858029, 2016). "The qRT-PCR based panel of MYC, MYCN, CCND1, CCND2, EGFR and FNDC3A was successful in detecting neoplasia with an overall accuracy of 54 % in S-CRN compared to that of 29 % in UC neoplastic samples." (PMID 27080994, 2016). "The median numbers of affected body segments in MYCN-amplified (MNA) tumours were 5 (European cohort) and 4 (COG cohort) compared to 9 and 11, respectively, in single-copy MYCN (MYCNsc) tumours (P < 0.001)." (PMID 25267348, 2015). "The expression of SHH pathway proteins is suppressed in tumours of MNA patients, suggesting that inhibition of SHH signalling contributes to MYCN initiated transformation." (PMID 26673823, 2015). "To validate the results obtained in cell cultures we analyzed the expression of some selected miRNAs in tumor tissue RNA specimens previously studied for LMNA and MYCN expression." (PMID 26439802, 2015). "Gross examination of the tumors in situ, prior to excision, revealed an intense dark red coloration across the whole tumor in the Th-MYCN mice, in contrast to the pale appearance of tumors in the Th-ALKF1174L/Th-MYCN GEM model." (PMID 24667968, 2014). "In this study the suggested tumor vascular phenotype in the Th-ALKF1174L/Th-MYCN model, which hinders the delivery of erythrocytes and causes a significantly slower R2*, may result in increased tumour hypoxia in the Th-ALKF1174L/Th-MYCN model compared with the Th-MYCN model." (PMID 24667968, 2014). "Increased expression of MYCN can be observed in cancers in the absence of overt aberrations of its gene structure, but about half of high-risk, metastatic neuroblastomas are characterized by amplification of the MYCN gene, leading to high mRNA and protein expression in tumor cells." (PMID 26029658, 2014). "In one of the tumors, the RB1 gene was unaltered, the MYCN gene was amplified and RB1 protein was expressed in the nuclei of the tumor cells." (PMID 24509483, 2014). "Combined treatment with crizotinib and an ATP-competitive mTOR inhibitor abrogated RPS6 phosphorylation, leading to reduced tumor growth and prolonged survival in ALKF1174L/MYCN-positive models compared to single agent treatment." (PMID 25228590, 2014). "MED3 is derived from a classical Group 3 tumour, MED4, and MED4R result from Group 3 tumours with MYCN gain." (PMID 24887326, 2014). "Among the MNA tumors (n=10), five tumor suppressor genes (among other genes) were underexpressed within the distal 1p: CAMTA1, KIF1B, PRDM2, FABP3, and CDKN2C; whereas MYCNOS and MYCN were the two top differentially upregulated genes on 2p." (PMID 23656755, 2013).
tumor (continued). "Indeed, a large number of oncogenes (e.g., ERBB2, MYCN, KRAS, etc.) are amplified at the level of the genome within various tumor types and this amplification not only underlies hypermorphic expression and/or function, but also serves to differentiate the tumor cells from normal surrounding tissues." (PMID 24202319, 2013). "On the other hand, NLRR1 is also a direct target of MYCN that nevertheless enhances EGF-mediated MYCN induction and accelerates tumor growth in vivo, exhibiting a biological function opposite to its homologue NLRR3 in NB." (PMID 24709709, 2013). "The implications of the existence of MYCN-amplified TEC are that these cancer cells disguised as endothelial cells are genetically unstable and involved in chemoresistance and tumor progression." (PMID 23162796, 2012). "Several candidate genes, such as MYCN, ERBB3, JUN, and IGFBP5, were also significantly upregulated, which keeps the tumor in a proliferative state." (PMID 22690114, 2012). "The novel tumour group comprised high-stage 11q-deleted tumours with low expression of ALK and MYCN, but high expression of various CNS and nervous system developmental genes." (PMID 21492432, 2011). "For this purpose we used cell lines with conditional MYCN or c-MYC expression, to screen a library of 80 conventional cytotoxic compounds for their ability to reduce tumor cell viability and/or growth in a MYC dependent way." (PMID 22132187, 2011). "To date, three genes have been identified that are frequently co-amplified with MYCN in NBs: DDX1 in 50% of the cases, NAG in 20% of the tumours, and MYCNOS in all cases." (PMID 19615087, 2009). "Each tumor in the TMA was designated to have a “good” or “poor” prognosis based on histopathology, age at diagnosis, MYCN copy number status, and stage." (PMID 18978946, 2008). "It is important to note that localized-NA tumors also express MYCN as well as c-MYC and it is likely that they are active because these tumors frequently show high tumor cell proliferation indices." (PMID 18851746, 2008). "Most tumours with LOH on 1p, increased NM23H1 copy numbers or MYCN amplification occurred in patients aged 12 months or more, those with advanced stage disease, and those who showed near diploidy or pseudodiploidy." (PMID 8932344, 1996). "We hypothesized that MYCN may be a target for PP2A, and that reactivation of PP2A may have a tumor suppressive effect on NBL." (PMID 41539997, 2026). "In this study, we showed that ONC201 treatment failed to decrease tumor vessel formation in non-MYCN-amplified SK-N-AS and SK-N-FI xenografts, whereas it elicited a significant decrease in neovascularization among MYCN-amplified SK-N-DZ xenografts." (PMID 40210723, 2025). "The subclones exhibited an interspersed spatial pattern, with pockets of MYCN and non-MYCN clones highlighted through neighbourhood enrichment within the tumour sample (inset)." (PMID 40335697, 2025). "Moreover, MYCN plays a pivotal role in maintaining NEPC, and interrupting MYCN through AURKA inhibitor CD532 leads to a notable decrease in tumor burden in patient-derived xenograft mice carrying N-Myc/myrAKT1 tumors." (PMID 39802403, 2025). "Furthermore, increased TRDMT1 expression is correlated with critical clinical features such as MYCN amplification and INSS staging, suggesting its role in tumour progression." (PMID 40984038, 2025). "While it fails to attenuate tumor neovascularization in non-MYCN-amplified NB xenografts, its effectiveness differs from that of its MYCN-amplified counterpart." (PMID 40210723, 2025). "The present study evaluated miRNA expression in plasma-derived sEVs from MYCN-amplified as well as non-amplified tumor samples." (PMID 41142119, 2025). "Silencing of PRMT5 leads to reduced MYCN levels and impaired tumor cell growth, suggesting that PRMT5 inhibitors could serve as potential therapeutic agents for MYC/MYCN-driven MB." (PMID 40365336, 2025).
tumor (continued). "Previous patient sequencing data have indicated that EZH2 may lead to the aberrant activation of MYCN in PTCL, thereby contributing to tumor progression." (PMID 40659662, 2025). "In turn, MYCN itself drives LIN28B expression, thus forming a feedback loop that exacerbates the disease by further suppressing let-7 miRNAs and sustaining high levels of MYCN, promoting the proliferation and maintenance of tumour cells." (PMID 40779030, 2025). "The results of the present study indicated that ONC201 exerts oncogenic, rather than tumor suppressive, effects in non-MYCN-amplified NB cells and xenografts." (PMID 40210723, 2025). "Studies have confirmed that SMAD9 also binds to the MYCN promoter to form a positive feedback loop, and gene silencing experiments have shown that SMAD9 knockout can significantly inhibit MNA-NB cell proliferation and tumor formation ability." (PMID 41244073, 2025). "In the early stages following MYCN overexpression, we observed a marked initial decline in GFP-positive cells, which was subsequently followed by the selective emergence and expansion of resistant tumor cell populations." (PMID 40943594, 2025). "In almost all multivariate regression analyses of prognostic factors, regardless of disease stage, MYCN gene amplification strongly predicted a poorer prognosis, including treatment response rate, time to tumor progression, and overall survival." (PMID 40115016, 2025). "MYCN-A3 suppressed tumor progression without toxicities, resulting in prolonged overall survival in MYCN-amplified NB." (PMID 40507292, 2025). "MYCN promotes the expression of miR-421, a microRNA that targets the 3′ untranslated region (UTR) of ATM mRNA, leading to decreased ATM protein levels and enhancing tumor cell survival and genomic instability." (PMID 41228232, 2025). "The patients with tumours classified as TMM negative had a significant better overall survival than the MYCN type cases (P 0.00017)." (PMID 40713849, 2025). "For example, in all MYCN-amplified tumours (n = 4), we identified two distinct subclones: with (C1) and without (C2) MYCN amplification, respectively." (PMID 40335697, 2025). "Notably, the MRGs-related signature outperformed MYCN in predicting NB patient prognosis and was adept at representing the tumor microenvironment (TME), tumor cell stemness, and sensitivity to the chemotherapeutic agents Cisplatin, Topotecan, and Irinotecan." (PMID 38962012, 2024). "While many of the TFs implicated in these developmental gene-regulatory networks are weakly or not at all expressed in NB tumours, we found that the targets of MYCN-related TFs (based on our analysis) are highly expressed in MYCN-amplified tumours." (PMID 38702304, 2024). "The prognostic signature was shown to be significantly associated with diagnosis at less than 18 months of age, favourable tumour histology, and lack of MYCN amplification on validation datasets." (PMID 38398114, 2024). "Knockdown of POSTN, but not FN1, significantly slows the migration rate of ALK/MYCN tumor cells in filling the wounded area." (PMID 38451815, 2024). "Initial studies have reported that tumor infiltration by NK cells was dependent on MYCN amplification, with MYCN non-amplified patient samples marked by higher infiltration." (PMID 39294470, 2024). "Here, we presented three cases of stage 4 NB with an 11q deletion, non-amplified MYCN, with pre-and post-CT tumor CNA data, where all patients displayed a poor response to treatment and CT resistance." (PMID 39356132, 2024). "When testing is feasible, MYCN amplification is absent (WHO Classification of Tumours Editorial Board, 2021)." (PMID 38544524, 2024). "In our study, tivantinib showed a specific anti-tumor effect in NB, especially given its selective effect on all the NB cell lines tested irrespective of the MYCN amplification status and without impacting non-cancerous fibroblast cells." (PMID 39458991, 2024).
tumor (continued). "Next, we examined how changing WNT signaling impacts the growth of MYCN and ALK/MYCN tumor cells." (PMID 38451815, 2024). "In this study, we demonstrate that MYCN regulated the expression of SESN1 in NB cells, and SESN1 regulated the cell proliferation, cell migration, and invasion of NB cells in vitro, and tumor growth and NB tumor‐bearing mice survival in vivo." (PMID 38516781, 2024). "Despite prior research demonstrating a correlation between MYCN expression, tumor relapse and therapy resistance, its complex role is not fully understood yet." (PMID 38826727, 2024). "The three tumor clusters highly expressed CDK4, CCND1, and MYCN, respectively." (PMID 38181797, 2024). "Despite this, its anti-tumor effect in MYCN-amplified NB is better than that in MYCN-non-amplified NB." (PMID 38336749, 2024). "Alternatively, this diagnosis may be obtained by demonstrating the alignment of the tumor methylation profile with the pHGG RTK1, pHGG RTK2, or pHGG MYCN subtypes." (PMID 38544524, 2024). "The tumour cells established in this work represent a tumour with MYCN over-expression but without RB1 inactivation or other genetic lesions." (PMID 37606819, 2024). "Serum LDH levels have found to rise with tumor burden, and high levels of LDH has been linked with poor prognosis, however independent of disease stage in MYCN amplified NBs." (PMID 38660306, 2024). "Upon treatment with JQ1, a bromodomain and extraterminal domain (BET) inhibitor, MYCN, MYCNOT, and mrtl nearly vanish, coinciding with a notable increase in apoptosis levels in pediatric embryonal tumor cell lines that rely on MYC to maintain an undifferentiated phenotype." (PMID 39333489, 2024). "The cells have then not been under influence of MYCN for the extended period after transformation which is the case for patient-derived or xenografted experimental tumours." (PMID 37606819, 2024). "While MYCN and mutant anaplastic lymphoma kinase (ALKF1174L) cooperate in tumorigenesis, how ALK contributes to tumor formation remains unclear." (PMID 38451815, 2024). "Furthermore, the Kaplan–Meier overall survival curves indicated that patients displaying high CTSD and low MYCN (H/L profile) mRNA expression had a better clinical outcome compared to those bearing a tumor with low CTSD and high MYCN (L/H profile) expression." (PMID 38611021, 2024). "MYCN amplification can be detected by multiple assays including FISH and DNA methylation profiling which allows both to identify the specific methylation class of this tumor and the MYCN amplification in the derived CNV plot." (PMID 37658995, 2024). "Tumor-specific super-enhancer profile analysis has led to sub-classifying ADRN cells into MYCN non-amplified low-risk, MYCN non-amplified high-risk, and MYCN-amplified categories." (PMID 38791942, 2024). "We showed that MYCN‐amplified tumor cells had higher levels of DDX3X expression than MYCN‐nonamplified tumor cells." (PMID 37975412, 2024). "SMI-z did not significantly differ between the groups with respect to MYCN status, DNA ploidy, INRG risk, or tumor size, but significantly differed in histological classification and INRG stage." (PMID 39164514, 2024). "We confirmed tumor and non-tumor origins of the cells by RB1 mutation, MYCN FISH analyses and examined the expression of cancer and stroma-related marker proteins." (PMID 39695086, 2024). "Pathologically, 59 cases were classified as poorly differentiated, and 18 were undifferentiated; 29 cases had tumor MYCN amplification, whereas 48 cases did not." (PMID 39585848, 2024). "The MYCN-transformed human foetal retina formed tumours that were not fully constrained to immature cPRs but also to a less extent developed expression of markers for e.g. ganglion cells." (PMID 37606819, 2024). "In contrast, the TARGET GNB/NB dataset does not show a clear clustering of samples based on the tumor entity or the MYCN amplification status in the overall distance matrix." (PMID 39449099, 2024).